ENSG00000274293
Gene: Miscellaneous RNA gene on chromosome 12 (38,150,050 to 38,150,138, forward strand). Ensembl gene ENSG00000274293.
Gene Ontology:
Biological process: chromatin remodeling